EWSR1 (EWS RNA binding protein 1)
Diseases named in the same sentence as EWSR1 in open-access papers (continued):
Sharing a sentence is not in itself a finding about the gene and the disease.
Ewing sarcoma (continued). "Ewing sarcoma (EWS) is a highly aggressive tumor that affects children and young adults, showing gene fusions involving one member of the FET family of genes (usually EWSR1) and a member of the ETS family of transcription factors, with EWSR1-FLI1 being the most common." (PMID 34345016, 2021). "Therefore, when Ewing sarcoma is pathologically suspected, but all seven types of known fusion genes are negative, analysis using an EWSR1 primer upstream of exon 7 should be considered." (PMID 34749732, 2021). "Thus, in the absence of doxycycline, A673 Ewing sarcoma cells express high levels of EWSR1-FLI1 (EWSR1-FLI1high), while those in the presence of doxycycline express low levels of EWSR1-FLI1 (EWSR1-FLI1low)." (PMID 34830820, 2021). "FUS is highly related to EWSR1, and both are members of the FET (FUS/TLS, EWS, and TAF15) family of RNA binding proteins, while FLI1 and its related genes are members of the ETS family of DNA binding proteins, and together the “FET-ETS” fusions represent nearly all cases of Ewing sarcoma." (PMID 33488267, 2020). "In addition to the EWSR1-ETS gene fusion, Ewing sarcoma is characterized by high CD99 expression." (PMID 26802024, 2016). "Therefore diagnosis of Ewing sarcoma, pPNET or PNET (NOS), should be based on analysis of EWSR1 gene rearrangement or immunohistochemical analysis of FLI-1 not only on histological findings, associated with a limited immunophenotype usually represented by expression of CD99." (PMID 25960901, 2015). "Also the FISH assay for rearrangement or dosage abnormalities of the EWSR1 oncogene at Ewing sarcoma locus 22q12 was negative." (PMID 24715974, 2014). "The new models may help identify small molecule inhibitors that act directly on EWSR1::FLI1 fusion proteins or other genetic vulnerabilities within the altered epigenome and transcriptome, potentially contributing to a better understanding of Ewing sarcoma tumorigenesis." (PMID 41002248, 2026). "Ewing sarcoma (ES) is an aggressive bone cancer driven by the oncogenic fusion-protein EWSR1::FLI1, which is not present in normal cells and is therefore an attractive therapeutic target." (PMID 39894896, 2025). "Ewing sarcomas (ES) are rare small round cell sarcomas often affecting children and characterized by gene fusions involving one member of the FET family of genes (usually EWSR1) and a member of the ETS family of transcription factors (usually FLI1 or ERG)." (PMID 37372318, 2023). "For example, during the work-up of a small round blue cell cancer, for which Ewing sarcoma may be one of the possible diagnoses, pathologists frequently interrogate biopsy samples with EWSR1-targeting FISH probes that “break apart” in the presence of an EWSR1-translocation." (PMID 35347250, 2022). "Observing that an EWSR1 knockdown did not affect HEK293T/17 growth on soft agar, we asked whether the fusion protein could re-create the sensitivity to the loss of EWSR1 observed in Ewing sarcoma cells." (PMID 34035145, 2021). "However, our PCA showed that EWSR1-NFATc2-translocated sarcomas are clearly distinct from EWSR1-ETS-translocated Ewing sarcomas, and confirm that EWSR1-NFATc2-translocated sarcomas also do not show any transcriptomic similarity with neither CIC-DUX4- nor BCOR-CCNB3-translocated sarcomas." (PMID 29416716, 2018). "CIC-DUX4 fusions have been demonstrated in up to two thirds of EWSR1 rearrangement-negative undifferentiated round cell sarcomas of pediatric and young adult patients, with expression profiling demonstrating a distinct gene signature and suggesting a distinct pathogenesis from Ewing sarcoma." (PMID 28141799, 2017). "Ewing sarcoma (EwS) is a rare, aggressive pediatric malignancy driven by FET::ETS family fusions (EWSR1::FLI1 in >85% of cases) with no established environmental risk factors." (PMID 41728338, 2026).
Ewing sarcoma (continued). "The study found that EWS/FLI-1 (EWSR1), as an RBP, was present in all Ewing’s sarcoma samples but absent in osteosarcoma, rhabdomyosarcoma, leiomyosarcoma, and malignant fibrous histiocytoma." (PMID 41019082, 2025). "In the latest WHO classification, undifferentiated small round cell sarcomas of bone and soft tissue are divided into four distinct categories: Ewing sarcoma (ES), round cell sarcomas with EWSR1::non-ETS fusions, sarcomas with BCOR genetic alterations, and CIC-rearranged sarcomas." (PMID 40722508, 2025). "Although bone marrow–derived MSCs can undergo transformation, and EWSR1::FLI1 silencing reverts 3D chromatin conformation toward an MSC-like architecture, Ewing sarcoma does not appear to co-opt canonical MSC lineage TFs as principal dependencies." (PMID 41444391, 2025). "The differential diagnosis includes Ewing sarcoma, BCOR-altered sarcoma, sarcoma with EWSR-1::non-ETS fusion, and other round cell tumors." (PMID 40722508, 2025). "The recent WHO classification identifies four main categories: Ewing’s sarcoma, round cell sarcoma with non-ETS EWSR1 fusions, sarcoma with CIC rearrangements, and sarcoma with BCOR alterations." (PMID 39941818, 2025). "Current research indicates that USRCS can be further categorized into Ewing sarcoma, URCS with EWSR1-non-ETS fusions, CIC-rearranged sarcoma, and sarcoma with BCOR genetic alterations." (PMID 40666499, 2025). "Although, in hpMSCs, overexpression of EWSR1::FLI1 remodels the chromatin landscape by redistributing H3K27me3, in Ewing sarcoma cell lines, depletion of KDM6B—but not KDM6A—exerts its main effects partly by restoring H3K27me3 levels at enhancers." (PMID 41085408, 2025). "Unlike classical Ewing sarcoma, this tumor exhibits a characteristic FISH pattern with not only the separation signal of EWSR1 but also a clear amplification at the 5' of the EWSR1 locus." (PMID 38254207, 2024). "Under the original impression of the possibility of Ewing sarcoma, an EWSR1 FISH examination was carried out and no rearrangement of the EWSR1 gene was identified, excluding the possibility of Ewing sarcoma." (PMID 36765856, 2023). "In consequence, in the absence of doxycycline, A673 Ewing sarcoma cells produce high levels of EWSR1::FLI1 (EWSR1::FLI1high), while in the presence of doxycycline, low levels of EWSR1::FLI1 (EWSR1::FLI1low) are achieved." (PMID 37511533, 2023). "These included olfactory neuroblastoma (excluded based on clinical absence of nasal involvement) and Ewing sarcoma (due to lack of membranous CD99 staining and a negative EWSR1 FISH test)." (PMID 38031161, 2023). "In summary, the EWSR1 knockdown in Ewing sarcoma yielded similar effects as knocking down EWS-FLI1 and different from an EWSR1 knockdown in a non-Ewing cell line." (PMID 34035145, 2021). "Two cases revealed an EWSR1‐NFATC2 fusion using the WGS calling pipeline; one had been diagnosed as an Ewing sarcoma and the other as an unusual sarcoma not otherwise specified arising from a nerve." (PMID 32573957, 2020). "Of 109 round cell tumours with pathology consistent with Ewing sarcoma, 15 (13.8 %) cases were FISH-positive without an identifiable EWSR1 fusion transcript, 4 (3.7%) were FISH-negative but RT–PCR positive and 4 (3.7%) were negative for both." (PMID 28141799, 2017). "It should be noted that SEs are typically absent at the EWSR1, FLI1, and ERG loci in Ewing sarcoma." (PMID 41444391, 2025). "In our study we did not detect Ewing sarcoma with distinct NTRK and EWSR1 fusions." (PMID 35295613, 2022). "While evidence of direct binding of EWSR1-Fli1 to miR-30a-5p is lacking, over-expression of miR-30a-5p leads to reduction of cell proliferation and invasion as well as reduced CD99 expression in multiple Ewing sarcoma cell lines." (PMID 26204834, 2015).
Ewing sarcoma (continued). "Although NKX2.2 immunohistochemistry and EWSR1 rearrangement studies were not available in our setting to definitively exclude BCOR- or CIC-rearranged sarcomas, the characteristic morphology and diffuse membranous CD99 positivity strongly supported the diagnosis of Ewing sarcoma." (PMID 41278275, 2025). "One possible explanation is that there is no selectivity for specific chromosomes in the EWSR1/FLI1-dependent induction of aneuploidy, but during subsequent cell divisions, cells that inherit particular chromosomes manage to survive and expand during Ewing sarcoma development." (PMID 33293370, 2021).
sarcoma (259 papers, 2007 to 2026). A usually aggressive malignant neoplasm of the soft tissue or bone. "FUS and EWSR1, participants in other sarcoma fusion oncogenes, are both implicated in familial ALS27–29." (PMID 38326311, 2024). "This gene is implicated in a wide range of sarcoma subtypes, each characterized by distinct EWSR1 gene fusions that engage with a diverse array of partner genes." (PMID 38339014, 2024). "We also review the literature on EWSR1-NFATC2 translocation-associated sarcomas and use of pazopanib in bone sarcomas." (PMID 37736255, 2023). "As ES CTC tend to spread via the vasculature, and as ES is relatively more common than other forms of EWSR1 translocation-associated sarcoma, several studies to monitor disease activity have been undertaken using different forms of liquid biopsy." (PMID 33669307, 2021). "We then compared the secondary genomic landscape of EWSR1-NFATc2 fusion positive sarcomas to other classical Ewing and Ewing-family variant samples from the FMI database." (PMID 34021224, 2021). "Overall, for EWSR1-associated sarcomas in particular, the sensitivity of PCR in combination with the ability to enrich CTC indicates that liquid biopsies that incorporated these elements have an advantage over other methods." (PMID 33669307, 2021). "Here we present the largest cohort of genomically profiled EWSR1-NFATc2 fusion positive sarcomas and assess secondary alterations associated with the fusion relative to other EWSR1 fusion sarcomas." (PMID 34021224, 2021). "While this data serves to bolster previous findings of the unique nature of the EWSR1-NFATc2 fusion, this study also associates EWSR1-NFATc2 fusion positive sarcomas with activation of the mTOR pathway." (PMID 34021224, 2021). "CCSA is known as a translocation-associated sarcoma that is associated with EWSR1-rearrangements, leading to aberrant MET expression." (PMID 34885165, 2021). "An update is provided on research relevant to the improvement of the early detection of relapse in sarcomas with EWSR1-associated translocations, in the contexts of biology, diagnosis, and liquid biopsy." (PMID 33669307, 2021). "This review summarises developments for sarcomas that are associated with the translocation of EWSR1 and similar genes." (PMID 33669307, 2021). "In fact, this finding should serve as a first diagnostic hint of the EWSR1-NFATC2-translocated sarcomas." (PMID 31049020, 2019). "ZNF384 fusions to TAF15 and Ewing’s sarcoma gene EWSR1, caused by chromosome translocations have been implicated in acute leukemia." (PMID 24465633, 2014). "In EWSR1 fusion gene expressing sarcomas, one EWSR1 allele is disrupted as a result of chromosomal translocation." (PMID 17912356, 2007). "Additionally, the formation of EWSR1 fusion genes in EwS results in the loss of one or both wild-type EWSR1 alleles in sarcoma cells." (PMID 41301081, 2025). "Cytogenetic and CGH/FISH analyses in EwS and related EWSR1 fusion tumors (e.g., desmoplastic small round-cell tumors) have reported cases where the formation of EWSR1-fusion genes in EwS results in the loss of one or both WT EWSR1 alleles in the sarcoma cells." (PMID 41301081, 2025). "EWSR1 stands out as the gene most commonly associated with translocations in sarcomas." (PMID 38339014, 2024). "Interestingly, while such neo-genes were first associated with EWSR1 fusion proteins, when examining 18 other oncogenic chimeric transcription factor-driven sarcoma types, exquisitely specific neo-transcripts were identified for each of these entities." (PMID 38611033, 2024). "The study suggested that the loss of EWSR1 may be a part of the molecular pathogenesis of EWSR1-expressing sarcomas because its tumor cells lack one EWSR1 allele due to the formation of the fusion gene." (PMID 36875767, 2023).
sarcoma (continued). "Within its limitations, our systematic review underlines an underreported problem in the diagnosis of melanoma and sarcoma, informs physicians about features that can make differential diagnosis difficult, and highlights the importance of searching for EWSR1 translocation in the diagnostic process." (PMID 37509250, 2023). "Although little is known about the functional role of CREB in sarcomas, pathogenic translocations between EWSR1 and CREB or its homologue ATF1 in clear cell sarcoma, another fusion-driven mesenchymal neoplasia, point to a major functional role in mesenchymal tumorigenesis." (PMID 35556229, 2022). "Recently, it has been proposed that sarcomas harboring a fusion of POU2AF3 with EWSR1 form a novel entity that often originate from the head and neck region, especially from the sinonasal track." (PMID 40134582, 2025). "Round cell sarcoma with EWSR1-non-ETS fusions includes two distinct entities, the EWSR1::NFATc2- and the EWSR1::PATZ1-fusion sarcomas." (PMID 40948502, 2025). "Although EWSR1 alterations are well-established oncogenic drivers in specific sarcoma subtypes, their role in CS is currently unclear." (PMID 41419593, 2025). "We established a novel cell line (PF1095) carrying a EWSR1::POU2AF3 fusion from the malignant pleural effusion of a 25-year-old sarcoma patient." (PMID 40134582, 2025). "The EWSR1::PATZ1 gene fusion was initially described in sarcomas, with only four published series documenting approximately 30 cases to date." (PMID 40575153, 2025). "Genes encoding the RNA-binding proteins FUS, EWSR1, and TAF15 (FET proteins) are involved in chromosomal translocations in rare sarcomas." (PMID 40852926, 2025). "Most of the samples were diagnosed as Ewing/Ewing-like sarcomas and tested for the presence of the EWSR1 BrAp rearrangement." (PMID 40718211, 2025). "Genes encoding the RNA-binding proteins FUS, EWSR1, and TAF15 (FET family proteins) are frequently involved in chromosomal translocations in sarcomas." (PMID 40852926, 2025). "We found that PRMT1 and PRMT5 expression, along with MEP50 the obligate cofactor of PRMT5, are generally higher in multiple sarcoma types, including EWSR1::FLI1 and EWSR1::ERG fusion-positive ES tumours, than in breast and lung cancer." (PMID 40823091, 2025). "PPMS with EWSR1::CREB1 fusion is an exceedingly rare low-grade malignant sarcoma, typically found in the bronchi and lung parenchyma." (PMID 38421462, 2024). "The latest research findings and novel treatment approaches for EWSR1/FUS::NFATC2 sarcoma involve molecular pathology research, immunotherapy, targeted therapy, and gene-editing techniques." (PMID 38254207, 2024). "In terms of histology, EWSR1/FUS::NFATC2 sarcoma typically presents as an undifferentiated small round cell sarcoma." (PMID 38254207, 2024). "These eventually yielded a variety of low and high-grade tumors including an angiomatoid fibrous histiocytoma with EWSR1::CREM fusion, a pleomorphic xanthoastrocytoma, and a DICER 1 associated sarcoma." (PMID 38764578, 2024). "Although EWSR1/FUS::NFATC2 sarcoma has its unique FISH presentation, due to its rarity and non-exclusive molecular genetic features, the diagnosis of this tumor must be combined with histology and immunohistochemistry." (PMID 38254207, 2024). "The rarity of EWSR1-CREM fusion sarcomas poses a challenge in treatment, highlighted by the development of pulmonary metastases and disease progression after surgical excision in this patient despite the lack of an effective targeted therapy." (PMID 38674190, 2024). "Some studies have shown that the prognosis of EWSR1/FUS::NFATC2 sarcoma is related to factors such as age, tumor size, lymph node metastasis, and surgical resection." (PMID 38254207, 2024). "Immunohistochemical staining shows that EWSR1/FUS::NFATC2 sarcoma often expresses markers such as CD99, NKX3.1." (PMID 38254207, 2024).
sarcoma (continued). "For certain situations, such as EWSR1::POU5F1 sarcoma and rare myoepithelial sarcoma, validation using EWSR1/FUS::NFATC2 fusion probe is necessary." (PMID 38254207, 2024). "In summary, we have presented three cases with uncommon GF partners of EWSR1 in sarcomas, with two of them being previously unreported." (PMID 38339014, 2024). "This article reports four cases of EWSR1::NFATC2 sarcoma, reviews the literature, and explores the clinical and pathological characteristics as well as molecular genetic features of this tumor." (PMID 38254207, 2024). "Rearrangement of Ewing Sarcoma breakpoint region 1 (EWSR1) was the first example of a cytogenetic abnormality in sarcoma." (PMID 38339014, 2024). "In terms of clinical characteristics, EWSR1/FUS::NFATC2 sarcoma mainly occurs in young males, with a male-to-female ratio of approximately 3:1." (PMID 38254207, 2024). "Due to the focal expression of epithelial markers such as CK and EMA in some cases of EWSR1/FUS::NFATC2 sarcoma, combined with morphological features, it can be easily misdiagnosed as an myoepithelioma." (PMID 38254207, 2024). "In terms of prognosis, EWSR1/FUS::NFATC2 sarcoma typically requires treatment such as surgical resection, radiation therapy, and chemotherapy." (PMID 38254207, 2024). "This suggests the possibility of EWSR1/FUS::NFATC2 sarcoma and can be validated using EWSR1::NFATC2 or FUS::NFATC2 fusion probe and NGS." (PMID 38254207, 2024). "These research results and novel treatment approaches provide new insights and directions for the treatment and management of EWSR1/FUS::NFATC2 sarcoma." (PMID 38254207, 2024). "In terms of clinical, radiological, histological, and FISH detection findings, EWSR1::NFATC2 fusion sarcoma exhibits distinct histopathological and molecular genetic features." (PMID 38254207, 2024). "In recent years, with the development of next-generation sequencing technology, some tumors associated with EWSR1 gene rearrangements have shown unique histological and molecular genetic characteristics, such as EWSR1/FUS::NFATC2 sarcoma." (PMID 38254207, 2024). "EWSR1/FUS::NFATC2 sarcomas have a preference for the bone and consist of round to spindle cells arranged in cords, nests, and trabeculae on a myxohyaline background." (PMID 36983010, 2023). "We showed that mRNA capture sequencing has a higher sensitivity than FISH by the detection of a known pathognomonic fusion in six FISH-negative sarcoma cases and confirmed the presence of four secondary fusion transcripts in EWSR1-NFATC2-positive patients." (PMID 36232302, 2022). "Second, the expression of wt ATF1 is retained in CCS, in contrast to several sarcomas driven by fusion proteins containing EWSR1, in which expression of the wt form of the EWSR1 fusion partner is lost." (PMID 35477713, 2022). "EWSR1 gene fusion was found in 6 cases of sarcoma, and FGFR2 fusion in 1 case of cholangiocarcinoma and 1 case of salivary duct carcinoma." (PMID 36088851, 2022). "Fusions between EWSR1 and partner genes often define pathological subtypes of sarcoma, and thus, their higher incidences in AYAs reflect the higher incidences of the corresponding subtypes." (PMID 36433963, 2022). "Significant differences in morphology, transcriptional profile, and behavior are found when comparing sarcomas harboring EWSR1::NFATC2 and FUS::NFATC2 fusions." (PMID 36555836, 2022). "We also diagnosed other types of sarcomas for three patients with rearrangement of the EWSR1 gene: one extraskeletal myxoid chondrosarcoma, one myoepithelial carcinoma, and one desmoplastic round cell tumor." (PMID 36164527, 2022). "This is in line with previous findings demonstrating that sarcomas with EWSR1-NFATC2 fusions not only show characteristic clinicopathological features but also segregate from other types of URCS on a molecular level." (PMID 36232302, 2022).